MET (MET proto-oncogene, receptor tyrosine kinase)
Diseases named in the same sentence as MET in open-access papers (continued):
Sharing a sentence is not in itself a finding about the gene and the disease.
head and neck squamous cell carcinoma (47 papers, 2010 to 2025). A squamous cell carcinoma that arises from any of the following anatomic sites: lip and oral cavity, nasal cavity, paranasal sinuses, pharynx, larynx, and salivary glands. "Moreover, crizotinib has also been found to target head and neck squamous cell carcinoma carrying MET point mutations (R1004)." (PMID 40696350, 2025). "Herein, we compared the molecular profiles and clinical significance of CTCs based on the expression of epithelial-related markers (EPCAM, EGFR, and MET) in patients with head and neck squamous-cell carcinoma (HNSCC)." (PMID 40699639, 2025). "HGF/c-MET signaling is involved in the metabolic reprogramming of tumor cells in head and neck squamous cell carcinoma regulating cell proliferation and invasion capabilities and affecting immune surveillance and activation in the tumor microenvironment." (PMID 40823073, 2025). "Inhibition of RTK pathways, which support proliferation and stemness in head and neck squamous cell carcinoma, can be partially offset by c-MET." (PMID 37373393, 2023). "A pathogenic gene alteration T230M was identified in the SEMA domain of the MET gene, which was reported in a sample of head and neck squamous cell carcinoma." (PMID 32083130, 2020). "Here, we evaluated synergistic antitumor efficacy of EGFR × MET targeting bispecific antibody, amivantamab with PD-L1 immunotherapy, pembrolizumab in head and neck squamous cell carcinoma (HNSCC) and lung squamous cell carcinoma tumor–bearing humanized patient-derived xenograft (PDX) models." (PMID 38916448, 2024). "Subsequently, the HNC018 has demonstrated its anti-proliferative and anticancer activities towards the head and neck squamous cell carcinoma cell lines, along with displaying the stronger binding affinities towards the MET, STAT3, and AKT than the standard drug cisplatin." (PMID 37373393, 2023). "c-MET upregulation can be found in the majority of head and neck squamous cell carcinomas." (PMID 35081970, 2022). "The correlations of MET expression levels with clinical significance and survival rates in head and neck squamous cell carcinoma (HNSCC) patients were further analyzed from the TCGA dataset." (PMID 39991569, 2025). "MET is frequently overexpressed in head and neck squamous cell carcinoma (HNSCC) and degraded by c-CBL E3-ubiquitin ligase." (PMID 27244893, 2017). "The results showed that the mRNA and protein expression of GSK3B, PIK3CA, FN1, MET, and SPP1 was significantly upregulated in head and neck squamous cell carcinoma tissues, while MAPK3 was significantly downregulated." (PMID 39323640, 2024). "In head and neck squamous cell carcinoma (HNSCC), CTTN induces gefitinib resistance by attenuating EGFR and c-MET degradation." (PMID 36831511, 2023). "In head and neck squamous cell carcinoma, over half of the patients overexpress HGF which stimulates MET to induce the proliferation of cell cycle genes by activating STAT3 in the TME." (PMID 37727377, 2023). "An aberrant HGF/c-MET signaling can lead to uncontrolled proliferation, motility, invasiveness, and angiogenesis and can play an essential role in the development, progression and survival of cancer including head and neck squamous cell carcinoma (HNSCC)." (PMID 35081970, 2022). "Although the receptor tyrosine kinase (RTK) MET is widely expressed in head and neck squamous cell carcinoma (HNSCC), its prognostic value remains unclear." (PMID 26909606, 2016). "c-MET phosphorylation has been reported in Non-Small Cell Lung (NSCLC) carcinoma, Head and Neck Squamous Cell Carcinoma (HNSCC), and other carcinomas." (PMID 21283737, 2011).
squamous cell carcinoma (47 papers, 2011 to 2025). A carcinoma arising from squamous epithelial cells. "In our study, PD-L1 expression was significantly higher in squamous cell carcinomas and lower in adenocarcinomas, and was positively associated with MET and KRAS mutations, as well as the wild-type EGFR gene state." (PMID 38394518, 2024). "Finally, MET dysregulation can occur via gene mutation, most notably the MET exon 14 skipping mutation seen in about 3–4% of adenocarcinoma and 2% of squamous cell carcinoma but in higher frequencies in adenosquamous carcinoma (6%) and pulmonary sarcomatoid carcinoma (9–22%)." (PMID 37509224, 2023). "For instance, transactivation of MET coincides with increased expression of EGFR in human epidermoid carcinoma." (PMID 32316583, 2020). "Within HN group, HGF/c-MET was detected in 7 of 17 (40%) squamous cell carcinomas (HN1, HN5, HN7, HN8, HN21, HN25, HN26), and 4 of 16 (25%) non-squamous cell carcinomas (HN12, HN15, HN16, HN33)." (PMID 21283737, 2011). "Similarly, Ren and co-authors reported shorter DSS and OS in patients with c-MET overexpression in squamous cell carcinoma and adenocarcinoma of the esophagus." (PMID 35406455, 2022). "Increased MET phosphorylation was reported in EGF-stimulated human epidermoid carcinoma." (PMID 32316583, 2020). "We examine the potential prognostic and predictive roles of EGFR variant III mutation, EGFR gene copy number (GCN), human papillomavirus (HPV) infection, c-MET and p16INK4A protein expression in recurrent or metastatic squamous cell carcinoma of the head and neck (R/M SCCHN)." (PMID 21352589, 2011). "The overexpression of MET was seen in all three patients with adenoid cystic carcinoma and is in line with other studies; however, to our knowledge, this is the first report of an overexpression also in carcinoma ex pleomorphic adenoma and primary squamous cell carcinoma." (PMID 33296026, 2021). "Furthermore, a retrospective study analyzing oropharngeal squamous cell carcinoma samples revealed a lack of statistical significance between MET mutations or c-Met expression and clinicopathological outcomes." (PMID 28441771, 2017). "AlK-independent resistance includes bypass activation, such as MET and RAF pathway activation or phenotypic transformation, which can be transformed into SCLC and squamous cell carcinoma." (PMID 38961982, 2024). "The ER-positive breast adenocarcinoma cell line MCF-7 was used as a positive control and the epidermoid carcinoma cell line A431 for EMT and MET genes, respectively." (PMID 36768815, 2023). "In squamous cell carcinomas, EGFR is activated by MET, contributing to tumorigenesis." (PMID 33204717, 2020). "In addition, HT1080 fibrosarcoma and A431 epidermoid carcinoma cells likewise expressed both NRP1 and MET especially under chemically induced hypoxia, thus being potential targets of rhodocetin-αβ as well." (PMID 29854288, 2018). "Moreover, TGF-β negatively regulates c-MET and HGF mRNA levels in human squamous carcinoma cells." (PMID 29238047, 2017). "In NSCLC, MET gene has been shown to be amplified in 21-24% of tumors and the impact of MET CN on prognosis is histological subtype dependent: MET amplification with a poorer prognosis in patients with adenocarcinoma but not in those with squamous cell carcinoma." (PMID 23379953, 2013). "However, even in one type of cancers, e.g., NSCLC, the impact of c-MET copy number on prognosis is a histological subtype dependent: c-MET amplification with a poorer prognosis in patients with adenocarcinoma but not in those with squamous cell carcinoma." (PMID 27923392, 2016).
triple-negative breast carcinoma (45 papers, 2015 to 2025). An invasive breast carcinoma which is negative for expression of estrogen receptor (ER), progesterone receptor (PR), and human epidermal growth factor receptor 2 (HER2). "M-sEV film-coated polylactic acid-glycolic acid copolymer nanoparticles immobilize the mesenchymal-epithelial transformation-binding peptide (c-MET), which has a high affinity for c-MET overexpressed in triple-negative breast cancer cells." (PMID 35832790, 2022). "Here, we investigated the therapeutic efficacy of OMO-1, a potent and selective c-MET inhibitor, in an immunocompetent intraductal mouse model for triple-negative breast cancer (TNBC)." (PMID 33731699, 2021). "Mouse models also suggest a critical role for the MET pathway during the development of triple-negative breast cancer." (PMID 26123926, 2015). "Consequently, the simultaneous overexpression of c-MET and EGFR in triple-negative breast cancer (TNBC) is associated with poorer clinicopathological outcomes and increased risks." (PMID 41234389, 2025). "Indeed, it was recently shown that MET inhibitors function synergistically with PARPis in suppressing growth of triple-negative breast cancer cells and HGSOC cells." (PMID 33213473, 2020). "In contrast, super-enhancers found in triple-negative breast cancer (ER−, PR−, HER2−) co-localized with the transcription factors FOXC1, MET, MYC, and ANLN." (PMID 36232979, 2022). "Here, we show that in triple-negative breast cancer cell lines NMDAR2B and MET proteins are coexpressed." (PMID 36139568, 2022). "In the context of triple-negative breast cancer (TNBC), c-MET is overexpressed in about 52% of TNBC patient tumors, and high c-MET expression is correlated with worse disease-free as well as overall survival." (PMID 33731699, 2021). "A phase II study of Foretinib (an oral multi-kinase inhibitor of MET, RON, AXL, TIE-2, and VEGF receptors) in patients with triple-negative breast cancer observed a clinical benefit rate of 46 %." (PMID 27894094, 2017). "Additionally, fibroblast secretion of HGF was found to activate MET and lead to EGFR/MET crosstalk, resulting in resistance to EGFR TKIs in triple-negative breast cancer." (PMID 40560045, 2025). "Increases in VEGF and CA9 and decreases in VEGFR2 with cabozantinib treatment have been observed in triple negative breast cancer, and increases in VEGF, CA9, MET, and IL-8 and decreases in VEGFR2 with cabozantinib treatment have been observed in castration-resistant prostate cancer." (PMID 34364385, 2021). "The triple-negative breast cancer (TNBC) cells MDA-MB-231 do not express estrogen receptor (ERα) nor HER2, but expresses c-MET, which is considered the main OC molecular target." (PMID 31590382, 2019).
cervical carcinoma (39 papers, 2009 to 2025). A carcinoma arising from either the exocervical squamous epithelium or the endocervical glandular epithelium. "A therapeutic strategy for the treatment of cancer could be idealised on targeting the PITPNA-AS1-associated signalling, which mediates the effects of c-MET on the proliferation, apoptosis and cell cycle in cervical cancer cells." (PMID 35057823, 2022). "For example, the lncRNA PITPNA-AS1/miR-876-5p/c-MET axis regulates the cell cycle, and promotes the progression of cervical cancer." (PMID 38164289, 2024). "Considering that c-MET overexpression has recently been shown as a prognostic marker in cervical cancer, the potential role of Met inhibition in cervical cancers with 2q37 deletions is a worthy area for future studies." (PMID 34620846, 2021). "The MET proto-oncogene receptor tyrosine kinase (c-Met) is overexpressed in multiple malignancies, such as the cervical cancer cell line CaSki, and is related to the metastasis, proliferation, and invasion of cancer." (PMID 32168899, 2020). "In the present study, HPV-16 E6 was confirmed to regulate miR-23b indirectly through the DNA methylation of host gene C9orf3 and thus induce c-MET and inhibit apoptosis in cervical cancer cells." (PMID 28077801, 2017). "This in turn decreases the expression of c-MET and deactivates the subsequent signaling pathway to induce apoptosis in human cervical cancer cells." (PMID 28077801, 2017). "c-MET was also overexpressed in many human solid tumors including uterine cervix carcinomas and its overexpression served as an important prognostic indicator." (PMID 28077801, 2017). "We observed that MET downregulation decreased Slug levels in cervical cancer cells both in vitro and in vivo, suggesting its role in regulating E-cadherin expression in cervical carcinoma cells." (PMID 25888626, 2015). "Cervical carcinoma cells were transduced with lentiviral vectors containing anti-MET shRNAs that were established in our laboratory." (PMID 25888626, 2015). "In addition, verticillin, targeting MET/FAK/Src, inhibited the migration ability through HGF/MET deactivation in gastric and cervical cancer cells." (PMID 36430388, 2022). "In contrast to other studies where MET receptor silencing promoted apoptosis, we did not observe increased apoptosis in MET-deficient cervical carcinoma cells." (PMID 25888626, 2015). "We show that MET downregulation decreased cervical cancer cell proliferation." (PMID 25888626, 2015). "Dysregulation and sustained activation of several RTKs, including VEGFR, HER2/ErbB2, MET, EGFR, and PDGFR, as well as its downstream oncogenic cascades can lead to cervical cancer tumorigenesis, which are associated with poor prognosis and chemoresistance for cervical cancer." (PMID 39282148, 2022). "Crizotinib, an inhibitor of mesenchymal epithelial transforming factor (c-MET) and anaplastic lymphoma kinase (ALK), has shown promising anticancer effects in cervical cancer." (PMID 36561319, 2022). "Flow cytometry showed cell phenotype-specific expression pattern for VEGFR3, MET, and SLUG and revealed correlation with the amount of tumor-infiltrating lymphocytes at the early stages of cervical cancer progression." (PMID 32899940, 2020). "Our literature search, as well as published meta-analyses and reviews, gives grounds for stating that the involvement of FLT4, MET, and SLUG in cervical cancer pathogenesis has been poorly investigated as contrasted with other tumor types." (PMID 32899940, 2020).
sarcoma (39 papers, 2007 to 2024). A usually aggressive malignant neoplasm of the soft tissue or bone. "Abnormal HGF/MET signaling is implicated in the development and metastasis of various malignant tumors, including sarcomas." (PMID 38596618, 2024). "While MET mutations are rare in sarcomas, overexpression of MET is common and associated with poor clinical outcomes in patients with this disease." (PMID 38596618, 2024). "The activation of MET and Src signaling pathways have also been implicated in tumor progression of various sarcomas." (PMID 38434982, 2024). "CCSA is known as a translocation-associated sarcoma that is associated with EWSR1-rearrangements, leading to aberrant MET expression." (PMID 34885165, 2021). "MET protein was first discovered in a human osteogenic sarcoma cell line as a part of a hybrid gene generated by the fusion of translocated promoter region from chromosome 1q25 and MET." (PMID 34217156, 2021). "The results showed that high MET expression was associated with poor patient OS in HNSC, LUAD, OV, PAAD, sarcoma (SARC), and THYM." (PMID 33178590, 2020). "Exposure of sarcoma cells to [pazopanib + entinostat] caused activation of ERBB1, ERBB2, c-KIT, c-MET, and c-SRC." (PMID 31380285, 2019). "Exposure of sarcoma cells to [pazopanib + entinostat] caused activation of ERBB1 and c-SRC and in a cell-specific fashion, activations of ERBB2, c-KIT, and c-MET." (PMID 31380285, 2019). "Another undifferentiated pleomorphic sarcoma fulfilled the criterion for intermediate level copy number gain for MET (MET gene copy number ≥5.0/cell in ≥50% of cells) with an average MET gene copy number of 5.13/nucleus." (PMID 25844809, 2015). "By applying these strict criteria we found that at least 6% of undifferentiated pleomorphic sarcomas belong into this category and, therefore, represent candidates for clinical trials with MET inhibitors, e.g., small molecules." (PMID 25844809, 2015). "MET protein expression was observed in 2.6% of the cases, all of which were either undifferentiated pleomorphic sarcomas or angiosarcomas, showing positivity rates of 14% and 17%, respectively." (PMID 25844809, 2015). "In summary, we investigated a comprehensive series of more than 400 adult-type sarcomas for MET and HGF overexpression as well as for MET gene amplification." (PMID 25844809, 2015). "The HGF/c-MET signaling pathway is critical in cell proliferation, motility, and invasion of several human sarcomas, but little is known about its biological functions in EpS." (PMID 25098767, 2014). "Although this a small study, we show that FLT may be used to predict responses to c-MET inhibitor or MDM2 inhibitor in diverse sarcoma sub-types." (PMID 32106426, 2020). "An ASPS and an unclassified high grade sarcoma each had prior MET inhibitor." (PMID 29162825, 2017). "Therefore, we provide evidence that these sarcoma entities are candidates for upcoming clinical trials with compounds inhibiting the HGF/MET axis." (PMID 25844809, 2015). "Clinical trials with MET inhibitors could be discussed for sarcoma patients but will require careful planning." (PMID 25844809, 2015). "Only few preclinical studies, however, dealt with inhibition of HGF/MET axis in sarcomas, but they could show antitumoral effects on growth, viability, invasion and metastasis in vitro and in vivo." (PMID 25844809, 2015). "We could demonstrate that angiosarcomas (either primary or radiation induced) and undifferentiated pleomorphic sarcomas represent those entities with a significant proportion of MET positivity." (PMID 25844809, 2015). "Notably, all tumors with MET overexpression were either angiosarcomas or undifferentiated pleomorphic sarcomas." (PMID 25844809, 2015). "Based on our findings first and foremost patients with angiosarcomas or undifferentiated pleomorphic sarcomas could be considered as these entities represent sarcoma types which show first evidence of potential dysregulation of the MET pathway." (PMID 25844809, 2015).